TMEM229B (transmembrane protein 229B)
Synonyms: C14orf83; FLJ33387
Tractability: Antibody: UniProt predicts a signal peptide or a membrane-spanning region.
Gene: Protein-coding gene on chromosome 14 (67,447,084 to 67,533,878, reverse strand). Ensembl gene ENSG00000198133.
Subcellular location: Membrane
Gene Ontology:
Molecular function: protein binding
Cellular component: membrane
Genetic constraint (gnomAD): Loss-of-function variants: 6 observed, 13.95 expected, observed/expected ratio (o/e) 0.43, 90% interval 0.23 to 0.85. The upper end of that interval is the gene's LOEUF score, 0.85, which puts it in group 3 of 6, group 1 being the genes least tolerant of losing a copy. Missense variants: 170 observed, 241.44 expected, observed/expected ratio (o/e) 0.7, 90% interval 0.62 to 0.8. Synonymous variants: 107 observed, 104.44 expected, observed/expected ratio (o/e) 1.02, 90% interval 0.88 to 1.2.
Homologues: Orthologues: chimpanzee TMEM229B (100% identical), macaque TMEM229B (99% identical), dog TMEM229B (98% identical), guinea pig TMEM229B (96% identical), mouse Tmem229b (96% identical), rat Tmem229b (96% identical), zebrafish tmem229b (76% identical). Paralogues in human: TMEM229A (28% identical).
Diseases named in the same sentence as TMEM229B in open-access papers:
TMEM229B is named in the same sentence as 12 diseases in open-access papers, as found by Europe PMC text mining. Sharing a sentence is not in itself a finding about the gene and the disease. The quoted sentences say what the papers report.
bladder cancer (1 paper, 2022). "To test the study hypothesis, in human bladder epithelial cells, we detected the expression of FBXO6, OAS1, and TMEM229B genes, as well as three different bladder cancer cell lines by using RT-qPCR technique." (PMID 36468020, 2022). "Contrary to bladder epithelial cells, bladder cancer cells expressed significantly higher levels of FBXO6 and TMEM229B genes." (PMID 36468020, 2022).
diabetes (1 paper, 2013). "Of note, the Tmem229B, Prss53 and Ttc28 genes, which have not been linked to β-cell functions or diabetes, showed strong signals in untreated islets but were strongly suppressed by STZ." (PMID 23828045, 2013).
esophageal squamous cell carcinoma (1 paper, 2022). Esophageal squamous cell carcinoma (ESCC) is a type of esophageal carcinoma (EC) that can affect any part of the esophagus, but is usually located in the upper or middle third. "Many studies showed that the TMEM family can be described as tumor suppressors or oncogenes, and TMEM229B was reported can be a potential antigen for esophageal squamous cell carcinoma mRNA vaccines." (PMID 36468020, 2022).
tumor (2 papers, 2022). "Therefore, these four tumor antigens (NLCR4, LCP2, TMEM229B, FCRL4) were considered as potential candidates for ESCC mRNA vaccine with immune activation and can be processed and presented by APCs to induce an immune response." (PMID 35734437, 2022).
cancer (1 paper, 2018). A tumor composed of atypical neoplastic, often pleomorphic cells that invade other tissues. "The screen also identified several genes and non-coding RNAs of unknown function, including C14orf142, TMEM229b, KB-1460A1.5, and KIAA0922, whose expression in human cancers would suggest a yet-to-be-described role in cancer progression and metastasis." (PMID 29904055, 2018). "Moreover, a detailed survey of immunohistochemical staining of human cancers indicated that SRPK1, KIF3B, C14orf142, NR2F1, and TMEM229B have significantly increased expression in the invasive zone of the primary tumors of these cancers as delineated by a pathologist." (PMID 29904055, 2018).
TMEM229B also shares sentences with these, for which no sentence is quoted: colon cancer (1 paper); head and neck cancer (1); lung carcinoma (1); melanoma (1); ovarian carcinoma (1); prostate carcinoma (1); schizophrenia (1).